CRP (C-reactive protein)
Diseases named in the same sentence as CRP in open-access papers (continued):
Sharing a sentence is not in itself a finding about the gene and the disease.
coronary artery disease (continued). "Thus, the researchers suggest, the recommendation that CRP measurements should be used in the management of patients with stable coronary artery disease ought to be removed from clinical practice guidelines." (PMID 20532236, 2010). "The other demonstrated in two large independent cohorts of diabetic subjects that the G allele was associated with increased risk of coronary artery disease compared to the A allele, independent of major CV risk factors; unfortunately CRP was not measured." (PMID 21029457, 2010). "In evaluating the quality of published evidence on CRP in the prognosis of patients with stable coronary disease we carried out a systematic review, meta-analysis, and meta-regression with five specific objectives: (i) To determine the quality of study reporting based on a systematic review." (PMID 20532236, 2010). "In the LURIC Study cohort the A-allele of the rs2259816 polymorphism in the HNF1A gene is associated with decreased CRP but not with coronary artery disease." (PMID 21062467, 2010). "We sought to evaluate the quality of prognostic research evidence for the association of C-reactive protein (CRP) with fatal and nonfatal events among patients with stable coronary disease." (PMID 20532236, 2010). "The possible function(s) of HNF1α are a focus of intense current interest following its recently reported associations in GWAS with plasma C-reactive protein (CRP), gamma-glutamyl transferase (GGT), LDL cholesterol and apolipoprotein and coronary artery disease." (PMID 21203500, 2010). "We searched MEDLINE (1966 to 2009) and EMBASE (1980 to 2009) and selected prospective studies of patients with stable coronary disease, reporting a relative risk for the association of CRP with death and nonfatal cardiovascular events." (PMID 20532236, 2010). "In a systematic review and meta-analysis of 83 prognostic studies of C-reactive protein in coronary disease, Hemingway and colleagues find substantial biases, preventing them from drawing clear conclusions relating to the use of this marker in clinical practice." (PMID 20532236, 2010). "Recent data also suggest that elevated serum CRP and urate levels may contribute to the development of coronary artery disease." (PMID 19804633, 2009). "The focus of most of the research attempting to link CRP expression and incidence of chronic diseases that are confounded by smoking status has been in the area of coronary heart disease (CHD), and a recent review provides a comprehensive analysis of this field." (PMID 19732183, 2009). "However, age, which was also correlated with Hs-CRP, showed positive correlation to severity of coronary disease in all age groups (P < 0.01, 0.02, 0.001 respectively)." (PMID 20508763, 2009). "A number of studies have demonstrated the utility of CRP as a sensitive biomarker of cardiovascular diseases, in particular, future coronary heart disease (CHD), independent of traditional risk factors." (PMID 18445267, 2008). "Having an elevated level of the acute-phase reactant C-reactive protein (CRP) is considered a strong, independent predictor of coronary heart disease, and is believed to play a direct role in the development of atherosclerotic plaque through effects on the vascular endothelium." (PMID 16674818, 2006). "It is therefore more likely that the found interactions between the CETP TaqIB polymorphism and elevated C-reactive protein, presence of renal dysfunction or ischemic heart disease are not biological meaningful." (PMID 16623947, 2006). "For example, a prospective study involving 15,828 patients with coronary heart disease showed that after multi-variable adjustments, circulating C-reactive protein (CRP) was not independently associated with an increased risk of adverse cardiovascular events, cancer mortality or all-cause mortality." (PMID 39118094, 2024). "On the other hand, CRP does not appear to be a risk factor for coronary heart disease." (PMID 38525188, 2024).
coronary artery disease (continued). "Epidemiological and multiple prospective cohort studies have demonstrated associations between C-reactive protein (CRP), leukocytes and their subgroups, and coronary artery disease (CAD) risk." (PMID 39323757, 2024). "The genetic associations suggest that targeting interleukin-6 pathways may reduce coronary artery disease risk but targeting C-reactive protein directly will not." (PMID 36736292, 2023). "Hence CRP is expected to be elevated when upstream inflammatory processes are active, but CRP does not necessarily have a causal role in the pathogenic inflammation of coronary disease or AS itself." (PMID 37914784, 2023). "However, CHIP carriers have higher CRP levels among patients with prior coronary artery disease." (PMID 36864496, 2023). "C-reactive protein (CRP), total white blood cell count, and neutrophil-to-lymphocyte ratio are three independent inflammatory predictors associated with a negative prognosis in coronary artery disease." (PMID 36766543, 2023). "Authorsanalyzed polymorphism in 5 genetic loci which showed strong association with CRP.It was observed that analyzed variants in the CRP locus showed no associationwith coronary artery disease, confirming the mediating, rather than causal roleof CRP in coronary artery disease." (PMID 39076864, 2023). "Interleukin 6 (IL-6) and C-Reactive Protein (CRP) play an important role in chronic periodontitis with coronary artery disease (CAD)." (PMID 37239434, 2023). "For example, a small sample size study in Chinese patients with angiography-proven coronary artery disease (CAD) has shown that the increase of plasma PCSK9 level was associated with the elevation in white blood cell counts (WBCC), fibrinogen and high-sensitivity C-reactive protein (hs-CRP)." (PMID 35252378, 2022). "Hs-CRP level was independently associated with the presence of cardiovascular events in TAK patients, and elevated hs-CRP could predict cardiovascular events in TAK patients with coronary artery disease." (PMID 35526024, 2022). "Although elevation of systemic inflammatory biomarkers as IL-6 and C-reactive protein (CRP) have been associated to short-term exposure to air pollutant, the precise inflammatory cell pattern associated with the main air pollutants in patients with ischemic heart disease remains undetermined." (PMID 35354890, 2022). "Linking mechanisms between periodontal disease and coronary heart disease include shared risk factors, increased fibrinogen, the role of white blood cell (WBC), the effect of bacterial LPS, bacteria, and the role of C-reactive protein (CRP), which acts as a strong biomarker." (PMID 34199122, 2021). "Moreover, our group has discovered that the in vitro migratory activity of CD34+ MNCs positively correlated with cardiovascular death, independently from other predictive factors, such as age, coronary artery disease, serum C-reactive protein, and glomerular filtration rate [82•]." (PMID 33651185, 2021). "Moreover, C-reactive protein (CRP), which is a sensitive marker of inflammation that predicts increased risk of coronary heart disease, increased with circadian misalignment, independent of sleep loss." (PMID 32219098, 2020). "Moreover, we could demonstrate a statistically significant correlation between pathologically elevated CRP levels and coronary heart disease (p < 0.0001)." (PMID 31936329, 2020). "However, cysC may still be influenced by some factors such as uncontrolled thyroid disease, corticosteroid use, smoking, elevated C-reactive protein (CRP) levels, coronary artery disease, and conditions with rapid cell turnover such as malignancies." (PMID 32182861, 2020). "In particular, the American Heart Association has established that C-reactive protein (CRP) is the best inflammatory marker to use as a proxy for cardiovascular disease and evidence to date supports use of CRP as an independent predictor of increased coronary heart disease risk." (PMID 33141863, 2020).
coronary artery disease (continued). "Furthermore, the association between PTSD and MSIMI persisted even after adjusting for indicators of coronary artery disease severity, such as Gensini score, left ventricular ejection fraction, resting perfusion defects, high-sensitivity C-reactive protein level, and statin and clopidogrel use." (PMID 32286655, 2020). "Nevertheless, data available from the PRIME study (multicenter prospective cohort designed to identify risk factors for coronary heart disease) could not reveal an association with SCD when assessed with other biomarkers such as IL-6 or CRP." (PMID 32093244, 2020). "Previous work associating CRP with coronary heart disease severity at a cross‐sectional level was not subsequently replicated by larger Mendelian randomization studies, suggesting that the results were the effect of reverse causation or a secondary effect of disease severity." (PMID 31693246, 2020). "The objective of this work was to study the ability of blood cells and their microparticles to transport monomeric and pentameric forms of C-reactive protein (mCRP and pCRP) in the blood of patients with coronary artery disease (CAD)." (PMID 33086769, 2020). "Consequently, our study suggests that upregulation of miR-33 may be a missing link between bad prognosis of ischemic heart disease and high serum CRP level." (PMID 31063484, 2019). "Using genetic variants as the unconfounded proxies of CRP concentration, Mendelian randomization meta-analysis of individual participant data from 47 epidemiological studies showed that CRP concentration itself was unlikely to be the modest causal factor in coronary heart disease." (PMID 29951057, 2018). "According to the guideline of the U.S. Preventive Services Task Force, genetic/genomic markers are not included among those non-traditional risk factors suggested in coronary heart disease risk assessment (carotid intima-media thickness and high sensitivity C-reactive protein)." (PMID 29445720, 2017). "Therefore, the lack of concordance between the effect of CRP genotypes and CRP levels on T2D and coronary heart disease risks argues against a causal role of CRP in the etiologies of these two diseases." (PMID 28178951, 2017). "In the Indian Atherosclerosis Research study 19, hs-CRP levels were quantified in 774 subjects with coronary artery disease (CAD) and 1,544 asymptomatic individuals." (PMID 27166776, 2016). "In these studies, the indirect reduction of blood CRP levels that accompanied treatment with statins was found to be independently and significantly related to event-free survival and/or decreased progression of documented coronary disease and/or major cardiovascular events." (PMID 24803739, 2014). "Indeed, based upon multiple prospective epidemiological studies, CRP is now recognized as an independent marker and powerful predictor for future risks of myocardial infarction (MI), stroke, and death from coronary heart disease (CHD) in individuals apparently free of known CVD." (PMID 24803739, 2014). "This study aimed to assess the relationship of serum inflammatory marker high sensitivity C Reactive protein (hsCRP), with the presence and severity of angiographically evaluated coronary artery disease (CAD)." (PMID 24550967, 2013). "We assessed whether the frequencies of CD4+LAP+ and CD4+CD25+ Treg cells were associated with age, lipid and lipoprotein fractions, fasting glucose, CRP, and the Gensini score which used to quantify the severity of coronary artery stenosis in patients with coronary artery disease (CAD)." (PMID 24385687, 2013). "We assessed whether the frequencies of Th22 and Th9 were associated with lipid and lipoprotein fractions, fasting glucose, creatinine, CRP, and the Gensini score which was used to quantify the severity of coronary artery stenosis in patients with coronary artery disease (CAD)." (PMID 24453425, 2013).
coronary artery disease (continued). "We studied C-reactive protein (CRP) in the prognosis of stable coronary artery disease because it is the most widely investigated (>100 studies) novel prognostic biomarker in such patients, and therefore the research might be expected to have reached reliable conclusions." (PMID 20532236, 2010). "After 4 weeks of continuous intervention, SGYXP significantly reduced the serum BNP, CRP, HA, and PCIII levels in patients with coronary heart disease." (PMID 40230703, 2025). "In our study, we addressed potential confounding by adjusting all analyses for multiple factors, including age, albumin, malignancy, total protein, coronary artery disease, blood urea nitrogen, creatinine, history of AKI, and hs-CRP." (PMID 40305332, 2025). "Among the quartile of patients undergoing imaging within 30 days from the ED visit, lower age, higher hemoglobin, CRP, and d-dimer, and previous VTE predicted a VTE finding at investigation, whereas female sex and ischemic heart disease were protective." (PMID 38954105, 2025). "Similarly, the Women’s Health Initiative found that postmenopausal women with WBC counts in the upper quartile had more than twice the risk of death from coronary heart disease compared to those in the lowest quartile, independent of CRP levels and traditional risk factors." (PMID 41465826, 2025). "Coronary artery disease (CAD) is a major global health issue, and its severity assessment via the C-reactive protein-to-albumin ratio (CAR) is cost-effective and simple." (PMID 40922854, 2025). "In their univariate analysis for predicting mortality within 90 days, the significant variables were: copeptin, CRP, glucose, age, NIHSS, atrial fibrillation, coronary heart disease, total anterior circulation syndrome and small-vessel occlusive." (PMID 39777314, 2024). "Statin use has been demonstrated to reduce C-reactive protein (CRP), a clinical marker of inflammation, in patients with various conditions, including chronic kidney disease, type 2 diabetes, and coronary artery disease." (PMID 39797174, 2024). "Exo‐miRNA‐21‐3p overexpression positively correlates with hs‐CRP and LDL‐C levels in patients with coronary artery disease, while it negatively correlates with HDL‐C." (PMID 38983683, 2024). "The multivariate logistic model for in-hospital and 1-year outcomes included age, previous coronary artery disease, GID score, C-reactive protein level, leukocyte count, systolic blood pressure, and oxygen saturation at admission." (PMID 39536208, 2024). "Effects on ischemic heart disease, total protein levels, and forced vital capacity were the most frequently mediated by LTL, whereas urate levels, CRP, BMI, BFM, and EA were the most common exposures." (PMID 38760657, 2024). "Subsequently, a multivariate logistic regression analysis was conducted, including ALB, CRP, HbA1c, WBC, LEU, urine glucose, coronary heart disease, catheterization, and glucocorticoid usage as variables." (PMID 38771840, 2024). "FFA, Hcy, CRP, FPG are positively correlated with coronary heart disease in elderly patients with type 2 diabetes." (PMID 39713052, 2024). "Several inflammatory markers including levels of neutrophils, albumin, C-reactive protein (CRP), lymphocytes, platelets, and the combination of certain ratios have been studied for prediction of diseases such as coronary heart disease and neoplasms." (PMID 39125344, 2024). "The IVW analysis revealed significant associations between coronary artery disease (CAD) and basophil count (IVW, OR 0.92, 95% CI: 0.84–1.00, P = 0.048), lymphocyte count (IVW, OR 1.10, 95% CI: 1.04–1.16, P = 0.001), and CRP levels (IVW, OR 0.87, 95% CI: 0.73–1.00, P = 0.040)." (PMID 39323757, 2024). "In 1996, Michael A Mendall investigated the relationship between chronic low-grade systemic inflammation (c-reactive protein, CRP) and coronary artery disease through a cross-sectional study." (PMID 36873405, 2023).
coronary artery disease (continued). "Age, percentage of coronary artery disease, percentage of atrial fibrillation, percentage of neutrophils, NHR, NLR, PLR, MLR, and CRP levels were higher in the poor prognosis group than in the good prognosis group." (PMID 37327299, 2023). "Compared to other biological indicators such as PLR, NLR, or C-reactive protein, SII possesses unique advantages, making it a better predictor of coronary heart disease." (PMID 38066657, 2023). "Statistically significant differences were detected in sex, age, time from injury to admission, coronary heart disease, ASA classification, CRP elevation, and D‐dimer elevation." (PMID 37310092, 2023). "Among those with a higher increased CRP level (> 3 mg/L), new cardiac complications; ischemic heart disease, HF, AF and ventricular arrhythmias, were more common than among patients with CRP levels < 1 mg/L, while Takotsubo cardiomyopathy was not statistically associated with this CRP level." (PMID 37119383, 2023). "first reported significantly elevated C-reactive protein (CRP) concentrations in patients with PCOS and indicated low-grade chronic inflammation to be a novel mechanism of coronary heart disease and type 2 diabetes in those women." (PMID 36714563, 2022). "Dietary fibre was also found to lower the concentration of C-reactive protein (CRP), a marker of inflammation in the body and a predictor of coronary heart disease." (PMID 35745200, 2022). "The lower PA group was significantly older, had a higher proportion of women, a higher incidence of history of coronary artery disease (CAD), higher interdialytic weight gain (IDWG), sarcopenia, higher C-reactive protein (CRP), ferritin levels, and lower ASMM." (PMID 35758371, 2022). "Furthermore, in small placebo-controlled randomized controlled trials, the combination of metformin and liraglutide may reduce the levels of the most atherogenic LDL subfraction and C-reactive protein in patients with coronary artery disease and new onset type 2 diabetes." (PMID 35208256, 2022). "The emotional regulation strategies of reappraisal and suppression were studied in relation to inflammation (C reactive protein, CRP), stress and coronary heart disease in a large cohort of adult offspring from the Collaborative Perinatal Project." (PMID 35187004, 2022). "In univariate analysis, patients who died were older, more likely to be male, more frequently had coronary heart disease or congestive heart failure, cardiac arrhythmia, COPD, chronic kidney disease, elevated leukocyte counts and C-reactive protein." (PMID 34638235, 2021). "This study identified five independent mortality predictors: severe coma (Glasgow Coma Scale [GCS] ≤8), past histories of malignancy and coronary artery disease (CAD), elevated C-reactive protein (CRP) levels (> 10 mg/dl), and bandemia (> 10% band cells)." (PMID 33902485, 2021). "As a biomarker of systemic inflammation, C-reactive protein was observed to be positively correlated with MHR values in various cardiovascular events, including stable and unstable coronary artery disease." (PMID 34916874, 2021). "Univariate Cox proportional hazard analysis demonstrated that independent predictors of all-cause mortality were age, SAS score, progressive AS, history of ischemic heart disease, PAD, serum albumin level, and C-reactive protein level." (PMID 34513029, 2021). "on patients with coronary artery disease, it was found that serum OSM and CRP levels were elevated in the patient group." (PMID 31576964, 2020). "In patients with T2DM and coronary artery disease, vitamin D alone has improved glycemia, GSH, hs-CRP, MDA, and nitric oxide." (PMID 33081175, 2020). "The same was true after adjustment for age, sex, BMI and fibrinogen as well as after additional adjustment for coronary artery disease, heart failure/left ventricular dysfunction, GFR, antiplasmin, PAI-1, TAFI, C-reactive protein (CRP) and cTnI-hs." (PMID 31280356, 2020).